IZUMO3 (IZUMO family member 3)
Description:
Plays an important role in the biogenesis of the acrosome during sperm development.
Synonyms: C9orf134; bA20A20.1
Tractability: Antibody: UniProt places it where antibodies can reach, with high confidence; UniProt predicts a signal peptide or a membrane-spanning region; its Gene Ontology location is reachable by antibodies, with medium confidence.
Gene: Protein-coding gene on chromosome 9 (24,542,952 to 24,545,946, reverse strand). Ensembl gene ENSG00000205442.
Subcellular location: Cell membrane; Cytoplasmic vesicle, secretory vesicle, acrosome inner membrane
Subcellular location (Human Protein Atlas): Acrosome; Equatorial segment
Pathways (Reactome):
Reproduction: Acrosome Reaction and Sperm:Oocyte Membrane Binding
Gene Ontology:
Molecular function: protein homodimerization activity
Biological process: acrosome assembly
Cellular component: inner acrosomal membrane; plasma membrane
Genetic constraint (gnomAD): Loss-of-function variants: 29 observed, 23.8 expected, observed/expected ratio (o/e) 1.22, 90% interval 0.91 to 1.65. The upper end of that interval is the gene's LOEUF score, 1.65, which puts it in group 6 of 6, group 1 being the genes least tolerant of losing a copy. Missense variants: 350 observed, 262.97 expected, observed/expected ratio (o/e) 1.33, 90% interval 1.22 to 1.45. Synonymous variants: 118 observed, 96.34 expected, observed/expected ratio (o/e) 1.22, 90% interval 1.05 to 1.43.
Homologues: Orthologues: chimpanzee IZUMO3 (99% identical), macaque IZUMO3 (94% identical), dog IZUMO3 (81% identical), pig IZUMO3 (80% identical), rabbit IZUMO3 (77% identical), rat Izumo3 (72% identical), mouse Izumo3 (70% identical).
Diseases named in the same sentence as IZUMO3 in open-access papers:
IZUMO3 is named in the same sentence as 1 disease in open-access papers, as found by Europe PMC text mining. Sharing a sentence is not in itself a finding about the gene and the disease.
IZUMO3 shares sentences with these, for which no sentence is quoted: male infertility (1 paper).